TMEM119 (transmembrane protein 119)
Diseases named in the same sentence as TMEM119 in open-access papers (continued):
Sharing a sentence is not in itself a finding about the gene and the disease.
tumor (continued). "Two populations were identified as tumor-associated macrophages (CD163+), with one having a more proinflammatory phenotype (TAM-Mac; tumor-associated macrophages) and moderate expression of TMEM119." (PMID 38758780, 2024). "Altogether, we conclude that a subpopulation of BrM + microglia have reduced Tmem119 expression in the brain metastatic tumor microenvironment." (PMID 38308250, 2024). "Less TMEM119+ cells were localized in the tumor periphery and tumor center in recurrent tumors compared to unresected tumors (47% vs 53% and 9% vs 13%, respectively) while more were localized in the infiltrative zone (44% vs 34%)." (PMID 39605004, 2024). "Within the region corresponding to myeloid cells, there was separation between cells with highest expression for markers of microglia (TMEM119+ and P2RY12+) and tumor-associated macrophages (iba1+ and CD163+)." (PMID 38758780, 2024). "As immune cells can use vessels as a route of migration to the tumor, we then evaluated the distance of TMEM119+ cells from blood vessels within the tumor." (PMID 39605004, 2024). "We then performed a cumulative analysis of the TMEM119+ cells using hierarchical clustering to represent the distance of these cells from the tumor center in both unresected and resected tumors." (PMID 39605004, 2024). "This analysis performed on the tumor-surrounding Tmem119+ cells revealed remarkable differences between WT and SorLA-KO microglia." (PMID 38499808, 2024). "The stromal expressions of ITGAL and ITGAX, together with tumor expression of TMEM119 in NSCLC, were demonstrated." (PMID 37835514, 2023). "Our results showed that Iba1+ cells accumulated in the peritumoral area during tumor progression, while TMEM119+ microglia was located in the intratumoral area." (PMID 37234161, 2023). "Tumor necrosis promotes metastasis and is associated with poor prognosis; the presence of ITGAL, ITGAX, and TMEM119 in tumor necrosis suggests their roles in facilitating NSCLC progression." (PMID 37835514, 2023). "We demonstrate that Tmem119+ MG adopt an amoeboid morphology in the tumor proximity and localize abundantly at the tumor edge, whereas Gal-3+ Mo/MΦ accumulate mostly within the tumor mass in both female and male animals." (PMID 33608526, 2021). "We assessed Tmem119 and Gal-3 expression in CD11b+ cells from tumor-bearing hemispheres by flow cytometry at day 14 post implantation." (PMID 33608526, 2021). "Iba1+Tmem119+ MG were the most abundant population in the adjacent brain parenchyma and in the peri‐tumor area." (PMID 33755340, 2021). "Similar to what occurred in KPC‐conditioned media treated primary microglia, we observed increased expression of Il‐1b and Arg1 in the hypothalami of tumor‐bearing animals compared to sham animals, whereas there was decreased expression of Nos2 and Tmem119." (PMID 32039522, 2020). "During this study, TMEM119 was found to be closely related to tumour microenvironment." (PMID 40219804, 2025). "Additionally, CIBERSORT and ESTIMATE algorithms were applied to examine the relationship between TMEM119 expression and tumour-infiltrating immune cells, as well as the tumour microenvironment." (PMID 40219804, 2025). "Like so, microglia, despite killing and phagocytizing tumor cells in the early stages of brain invasion, following the release of intrinsic factors, downregulate genes involved in phagocytic activity, such as Tmem119 or Trem2, switching from an anti-tumor phenotype to a pro-tumor phenotype." (PMID 40507830, 2025). "Notably, TMEM119+ microglia aggregated within invasive islands and were closely associated with GFP-expressing tumor cells." (PMID 39781357, 2025). "The Hom-MG-1 subgroup highly expressed the innate characteristic genes of microglia (Tmem119, P2ry12, Crybb1, Cst1, Gpr34, and Cx3cr1), poorly expressed tumor activation-related genes, and expressed early activation genes to a certain extent (Jun, Junb, Jund, and Fos)." (PMID 39867913, 2024).
tumor (continued). "Tumor-associated macrophages (TAMs) further divided into monocyte-derived brain macrophages (Mo-TAMs) expressed monocyte markers (TGFBI, VCAN, LYZ, and CLEC12A) and cells termed as Mg-TAMs expressed microglial signature genes (TMEM119, P2RY12, and P2RY13)." (PMID 39451239, 2024). "Interestingly, in vehicle condition 30% of the CD8+ T cells were in contact with the TMEM119+ cells and these contacts increased to 40% during tumor growth." (PMID 39278921, 2024). "In both LUAD and LUSC, the nuclear expression of TMEM119 in tumor cells is apparent; its presence in stromal and tumor necrosis could also be detected." (PMID 37835514, 2023). "Tmem119 also stained cells around the tumor edge and these cells displayed more ameboid morphology." (PMID 35309309, 2022). "Because TMEM119+ FIBs segregated distinctly across KRT14+ tumor nests and were significantly higher in proportion in BCC samples, we wondered whether they may have a unique gene expression profile that may functionally support tumoral growth and progression." (PMID 35687691, 2022). "Both P2RY12 and TMEM119 expression were retained in tumor tissue." (PMID 34286275, 2021). "Furthermore, 54.8% of the resident Mφ (TMEM119 + Iba1+) cell population detected in the tumor tissues of dLGG–10 mice was demonstrated to have a higher distribution ratio than those in the tumor control (14.4%), Lipo-DOX–2 (13.6%), and dLGG–10 + Lipo-DOX–2 (14%) group mice." (PMID 34439274, 2021). "Next, we performed IF staining of GBM specimens, attempting to determine if LAIR1 was on tumor-infiltrating MΦ or resident microglia using CD45 and transmembrane protein 119 (Tmem119), a microglia marker." (PMID 40591413, 2025). "First, we determined the optimal passage of primary tumour cells for co-culture by culturing from passage 0 (P0) to passage 6 (P6) and assessing immune marker expression (CD68, CD163, and TMEM119) via western blotting." (PMID 40420192, 2025). "Nevertheless, it is noteworthy that TMEM119-positive microglial cells were consistently observed in all pathological states examined, including TBI, tumor, infection, and spontaneous IVH." (PMID 39904881, 2025). "Through investigating the clinical prognosis and immunological implications of TMEM119 in STAD, the relationship between TMEM119, prognosis and tumour microenvironment was revealed." (PMID 40219804, 2025). "Multiplexed IF analysis focused on GAMs (murine IBA1, TMEM119, and CD206), astrocytes (murine GFAP), CAR T cells (human CD3), and tumor surface/proliferation markers (human EGFRvIII, and Ki67) within and surrounding tumor regions." (PMID 39521782, 2024). "However, it is difficult to solely investigate their roles in the tumor progression due to their similarity with infiltrated macrophages even with recent lineage-tracing and single-cell sequence identifying core microglia signature markers, TMEM119, P2ry12, and SALL1." (PMID 38238749, 2024). "PRDX6, MAGOHB, NUCKS1, DCAF13, and TXN displayed opposite trends on their potential facilitation of CTL function as well as correlations with immune checkpoints and TILs (tumor-infiltrating lymphocytes) compared to ITGAL, ITGAX, and TMEM119 in NSCLC." (PMID 37835514, 2023). "Meanwhile, matched tumor sample showed high levels of SSR2, Iba1 (26.5%), and TMEM119 (39.5%), and moderate levels of CD206 (8.81%) and CD163 (11.9%)." (PMID 35534852, 2022). "Most of the TMEM119+ FIBs appeared to be positioned peripherally and juxtaposed to KRT14+ tumor nests, to a greater extent than those observed for CLIC2+ and CEMIP+ FIBs or sparse ASPN+ FIBs." (PMID 35687691, 2022). "With immunostaining, we confirmed the presence of CD44+ microglia (also TMEM119+) in EPN and AEP tumor sections, indicating that some CD44+ TAMs were tissue-resident microglia or their derivatives." (PMID 34824203, 2021). "Cdkn2a acts as a tumor suppressor in ALL through regulation of the cell cycle and Tmem119 is involved in osteoblast differentiation." (PMID 33154494, 2020).
tumor (continued). "Firstly, we have quantified the proportion of proliferative tumor cells (Sox2+ Ki67+) present in or around the resection cavity borders where we also quantified blood-derived macrophages CD68+ Galectine-3+ and microglia cells TMEM119+Galectine-3−." (PMID 39605004, 2024). "Closed contact of TMEM119+ cells and the GFP+ tumor cells were also observed." (PMID 38238749, 2024). "In another study from the same group, TMEM119 expression was reported to be increased in tumor gastric tissues compared to its non-tumor counterparts, and this overexpression was associated with a shorter lifespan." (PMID 37936608, 2023). "TMEM119 and the RFP tracer overlapped very reliably in experimental tumors and these TMEM119+RFP+ microglial cells accounted for approximately 25% of all Iba1-positive cells of the tumor parenchyma." (PMID 34298846, 2021). "Meanwhile, we also observed that the TMEM119-non-resident macrophages were localized in the tumor tissues of each group of mice." (PMID 34439274, 2021). "Staining for Tmem119 and Gal-3 revealed a non-uniform cell distribution within the tumor, with the predominance of Mo/MΦ (Gal-3+) in the tumor core, and MG (Tmem119+) occupying the tumor periphery." (PMID 33608526, 2021). "We further examined and compared the dynamics and polarity of microglia/macrophages (Mφ) including resident Mφ (TMEM119 + Iba1+), M2-like Mφ (CD163 + Iba1+), and M1-like Mφ (iNOS + Iba1+) in the TME of the tumor control and dLGG–10, Lipo-DOX–2 and dLGG–10 + Lipo-DOX–2 group mice." (PMID 34439274, 2021). "Their data identified SALL1, TMEM119, P2RY12 as markers of microglia-derived GAMs that dominated the TME of primary tumors and TGFBI, CLEC12A and FXYD5 as markers of MDMs that outnumbered microglia in recurrence and were enriched at pimonidazole (PIMO)-positive hypoxic tumor regions." (PMID 40642066, 2025). "Importantly, nearly all (> 99%) of the infiltrating CD45high population were GFPlow, suggesting that Tmem119 is microglia-specific and is not expressed on tumor-infiltrating peripheral myeloid cells." (PMID 38308250, 2024). "Hence, our results suggest a potential functional signaling network of TMEM119+ FIBs with KRT14+ tumor cells driven through paracrine noncanonical WNT signaling." (PMID 35687691, 2022). "However, Iba1+ cells with low or no Tmem119 expression were most prominent within tumor lesions, most likely representing BrM infiltrating TAM‐MDM." (PMID 33755340, 2021). "We next performed multiplex immunofluorescence staining to evaluate the spatial distribution of TILs in BrM relative to tumor cells and TAMs using marker combinations that allow to discriminate TAM populations based on the expression of the macrophage marker Iba1 and the microglial marker Tmem119." (PMID 33755340, 2021). "Our results indicated that BCC FIB populations have lower overall entropy than those of PTS and that TMEM119+ FIBs show the most stability, suggesting that FIB I to III may display higher likelihoods of transition to those FIBs that are most juxtaposed to BCC tumor nests (FIB IV)." (PMID 35687691, 2022). "Microglial markers SALL1, TMEM119, and P2RY12 were minimally expressed among tumor-infiltrating cells, suggesting that microglia did not highly infiltrate the brain metastases in this patient." (PMID 37209684, 2023). "In the tumor core, a large proportion of the EYFP+ cells were expressing Iba1 (70% in control and 50% in treated mice) but not TMEM119." (PMID 31660979, 2019). "On the other hand, Itgal, Itgax, and Tmem119 in LL2 tumors were downregulated by taxifolin; their human counterparts (ITGAL, ITGAX, and TMEM119) displayed positive T cell dysfunction values, suggesting their negative impact on CTL-derived cytotoxicity in tumor cells." (PMID 37835514, 2023).
infection (21 papers, 2018 to 2025). The state of being infected such as from the introduction of a foreign agent such as serum, vaccine, antigenic substance or organism. "In the meantime, the majority of CD45lowCD11b+ cells expressed the TMEM119 marker, with these values remaining consistent throughout the infection." (PMID 40771825, 2025). "Conversely, control mice exhibit greater expression of Ccl5, Mmp8, Sfrp2, Tmem119, and Tnn after 14 days of infection." (PMID 37845223, 2023). "Due to the difficulty of discriminating microglia versus infiltrating monocyte-derived macrophages we assessed the stability of the microglial-specific marker TMEM119 post-infection." (PMID 37983247, 2023). "Treatment with PLX5622 2 weeks prior to infection reduced (CD45+CD11b+Tmem119+) microglia by 95% in the mouse brain when compared to the control chow as demonstrated by flow cytometry." (PMID 35277184, 2022). "We then established OVCAR-3 and A2780 cell lines stably overexpressing TMEM119 by lentiviral infection." (PMID 33731124, 2021). "Further indicating that microgliosis was induced by infection, we found significantly higher TMEM119 immunoreactivity in the CA1 and DG hippocampal sub-regions of ZIKV-infected mice." (PMID 31488835, 2019). "Qualitative analysis of confocal images of moderately infected thalamus showed that TMEM119+ cells underwent morphological alterations, such as swollen cell bodies and thicker cytoplasmic processes, compared to surveillant microglia prior to the infection (left and middle)." (PMID 35387656, 2022). "In addition, microglia related genes, and genes associated with microglial cell activation (Mki67, Cd40, Tmem119 and Cx3cr1) were significantly induced 4 days following VACV-Wyeth infection indicating the possible role of these cells in the induction of immune response in the brain." (PMID 30759813, 2019). "After infection, the number of (CD45+CD11b+Tmem119+) microglia in WT mice was lower than that of TMLeD/LeD mice at 3 dpi, but not at 5 dpi." (PMID 35277184, 2022). "By contrast, for TMEM119, MFI exhibited a significant increase at 3, 6, and 36 weeks PI (p < 0.05) in the hippocampus and cortex during the 36-week infection period." (PMID 33803262, 2021). "Over the course of infection, the total microglia population progressively downregulated CX3CR1, F4/80, TMEM119 and CD68, and progressively upregulated CD45." (PMID 34311763, 2021). "The expression of pro-inflammatory cytokines, but not M1 surface marker CD86, is likely associated with the acute microglial response occurring in the early phases of infection, also testified by the lack of TMEM119 downregulation." (PMID 36781876, 2023). "In contrast, CD11b+TMEM119- cells, corresponding to infiltrating macrophages, showed a significant increase in CD38 expression (1.43-fold, SD ± 0.17, p = 0.0042), supporting the idea that macrophages may contribute to the NAD+ depletion during the late stages of infection." (PMID 41362627, 2025).
neurodegenerative disease (16 papers, 2018 to 2026). A disorder of the central nervous system characterized by gradual and progressive loss of neural tissue and neurologic function. "We aimed to evaluate the potential of the microglial marker transmembrane protein 119 (TMEM119) in the cerebrospinal fluid (CSF) as a (differential) diagnostic biomarker for neurodegenerative diseases." (PMID 41488805, 2026). "Moreover, Nurr1 deficiency resulted in a significant proportion of DAM-like phenotype microglia, which is a recently identified subpopulation characteristically associated with neurodegenerative diseases, as determined by the changes of Cx3cr1, Itgax, Trem2, and Tmem119." (PMID 37990334, 2023). "It is worth mentioning that although TMEM119 represents a reliable homeostatic marker for microglia, its downregulation has been reported in neurodegenerative diseases and models for demyelination." (PMID 37781403, 2023). "The expression of microglial signature genes, including TMEM119, P2RY12, and CX3CR1, is gradually reduced with age or in neurodegenerative diseases, suggesting the loss of homeostatic microglial function." (PMID 34920745, 2021). "While microglial core genes (e.g., TMEM119 and P2RY12) were found to be conserved, differences between human and mouse microglial gene expression were apparent in genes responsible for phagocytosis, complement, and susceptibility to neurodegenerative diseases." (PMID 33540859, 2021). "TMEM119+ CD11c+ microglia (which may encompass more than one subset) has been recently identified as DAM, a subpopulation characteristically associated with neurodegenerative diseases and white matter aging." (PMID 34326766, 2021). "The AUC was 0.721 for the discrimination between AD and all other diagnostic groups and was the lowest (0.618) for the discrimination between AD and ALS, underlining that CSF TMEM119 may not be suitable for differentiating between different neurodegenerative diseases." (PMID 41488805, 2026). "To assess this, we evaluated whether commonly used markers of microglial activation, namely TMEM119 and AIF151,52, are also upregulated across neurodegenerative diseases." (PMID 29636460, 2018).
cancer (10 papers, 2020 to 2025). A tumor composed of atypical neoplastic, often pleomorphic cells that invade other tissues. "The results revealed that TMEM119 expression was significantly associated with age (P = 0.0092), cancer stage (P < 0.05), grade (P = 0.00029), and T stage (P < 0.0001)." (PMID 40219804, 2025). "TMEM119 is a member of the transmembrane proteins family, which is abnormally expressed in human cancers and associated with tumorigenesis." (PMID 32147967, 2020). "Taken together, TMEM119 is disclosed to act as an oncogenic factor by stimulating malignant behaviors of multiple cancer cells." (PMID 33731124, 2021). "Nevertheless, the detailed mechanism by which TMEM119 participates in carcinogenesis and cancer progression remains elusive." (PMID 33731124, 2021). "Transmembrane protein 119 (TMEM119) has been reported as oncogene in several human cancers." (PMID 33731124, 2021). "As a consequence, targeting TMEM119 is a potential strategy in overcoming cancer." (PMID 32545648, 2020). "TMEM119 is a member of the transmembrane proteins with important functions in cancer cells." (PMID 32545648, 2020). "Some cancer associated signaling, such as TGF-β pathway, could be altered by TMEM119." (PMID 33731124, 2021). "In addition, ITGAL, ITGAX, and TMEM119 were also strongly correlated with macrophages and other immune cell populations in LUAD and LUSC as well as across a panel of human cancer types." (PMID 37835514, 2023).
brain disorder (3 papers, 2019 to 2022). A disease affecting the brain or part of the brain. "It was recently described that TMEM119 is downregulated in microglia during neuroinflammation and brain disease (20, –, 24)." (PMID 36036510, 2022). "Together, these data indicate high applicability of Tmem119-EGFP mice and good applicability of Tmem119-CreERT2 mice to the study of brain disorders with potential monocyte contribution." (PMID 31371457, 2019).
vasculopathy (1 paper, 2017). "Further, both approaches reduce vasculopathy (vaso-obliteration, neovascularization, vascular leakage) and alter the activation of Tmem119+ retinal microglia." (PMID 28963474, 2017).
TMEM119 also shares sentences with these, for which no sentence is quoted: cervical carcinoma (2 papers); meningioma (2); Parkinson disease (2); astrocytoma (1); Brain atrophy (1); cerebral artery (1); cerebral atherosclerosis (1); cholangiocarcinoma (1); depression (1); endometrial cancer (1); epilepsy (1); frontotemporal lobar degeneration (1); gastric adenocarcinoma (1); head and neck squamous cell carcinoma (1); infectious encephalitis (1); laryngeal carcinoma (1); Lewy body diseases (1); lymphoma (1); malaria (1); mild cognitive impairment (1); myopia (1); neurological diseases (1); non-small cell lung carcinoma (1); oral cancer (1); peripheral neuropathy (1); prostate carcinoma (1); retinitis pigmentosa (1); schizophrenia (1); type 2 diabetes (1).